SOX9 (SRY-box transcription factor 9)
Diseases named in the same sentence as SOX9 in open-access papers (continued):
Sharing a sentence is not in itself a finding about the gene and the disease.
breast carcinoma (continued). "Further, we found that gene expression signatures from basal-like breast carcinoma cells with high Sox9 levels correlate with those from LATS1/2-deleted luminal mammary epithelial cells." (PMID 36443313, 2022). "Studies in mice have shown that cancers resembling sporadic human basal-like breast cancers can arise from the luminal ER-negative/Sox9-expressing population." (PMID 36443313, 2022). "The treatment of SOX9-knockdown breast cancer cells with apyrase, an ATP hydroxylase, suppressed tumor growth and increased drug sensitivity in nude mice." (PMID 34638242, 2021). "Shikonin directly targets the communication between breast cancer cells and preapodocytes via interruption of the miR-140/SOX9 signaling that is facilitated through EVs." (PMID 34069860, 2021). "In turn, HDAC5 promoted SOX9 nuclear localization via interaction with its HMGB domain (amino acids 1–181) in estrogen receptor-positive breast cancer cells." (PMID 34178647, 2021). "In breast cancer, the SOX9/FXYD3/Src axis is critical for promoting cancer stem cell function and tamoxifen resistance." (PMID 34270462, 2021). "Knocking out of SOX9 by the CRISPR-Cas system has represented it as a potential therapeutic target in breast cancer." (PMID 34768751, 2021). "The role of miR-185 has been investigated in various cancers including lung cancer, osteosarcoma and breast cancer by targeting SOX9, HK2, DNMT1 and E2F6, respectively." (PMID 33507687, 2021). "Although numerous studies have investigated the roles of SOX9 in cancers of the prostate and colorectum, few investigated molecular functions of SOX9 in breast cancer." (PMID 32398735, 2020). "To expand our observation, we utilized available mRNA expression and epigenetic data of SOX9 in breast cancer patients collected from The Cancer Genome Atlas (TCGA) database." (PMID 32398735, 2020). "The role of SOX9 in chemoresistance has been reported for multiple tumors as for breast cancer, glioblastoma, cervical cancer, gastric cancer and lung cancer." (PMID 33076370, 2020). "ROCR favors both transcription and nuclear export of SOX9 mRNA and its silencing in breast cancer cells reduces the cytoplasmic levels of SOX9 mRNA." (PMID 32957640, 2020). "For correlations of SOX9 expression with different clinicopathological factors of breast cancer patients, patients with high SOX9 expression levels seemed to be related to advanced tumor stages." (PMID 32398735, 2020). "The previous study found that the SOX9 staining was medium positive in tumor tissues of breast cancer, relative to other types of tumors, but exact relationship between SOX9 and clinical characteristics of breast cancer patients has not been shown." (PMID 32398735, 2020). "SRY‐Box 9 (Sox9) is certified as the target gene of miR‐215‐5p; furthermore, the inhibition effects of miR‐215‐5p on breast cancer cell migration ability and invasiveness are phenocopied by Sox9 slicing." (PMID 31538724, 2019). "It is unclear if these genes work in concert with each other; however, Sox9 is essential for mammary gland development, and it has been shown that silencing Sox9 reduced cellular proliferation and invasion, in breast cancer cell lines." (PMID 31040905, 2019). "Contrary to the expression of miR-190 as determined by RT-qPCR, western blot analysis revealed that the expression of SOX9 was much higher in ER− breast cancer cell lines compared with that in the ER+ breast cancer cell lines." (PMID 30658681, 2019). "Deacetylation is required for SOX9 nuclear translocation in tamoxifen-resistant breast cancer cells." (PMID 31690832, 2019). "For clinical relevance, high SOX9 and HDAC5 expression are associated with lower survival rates in breast cancer patients treated with tamoxifen." (PMID 31690832, 2019). "miR-190 inhibited Wnt/β-catenin signaling by targeting SOX9, and its expression inversely correlated with that of SOX9 in breast cancer samples." (PMID 30658681, 2019).
breast carcinoma (continued). "Meanwhile, overexpression of Sox9 converted the suppressive impact of miR‐215‐5p on the growth and metastatic‐related traits of breast cancer cells, suggesting that Sox9 is the downstream target of miR‐215‐5p." (PMID 31538724, 2019). "To determine the effects of Sox9 signalling in breast cancer tumorigenicity, we analysed cell clonogenicity, migration and invasion capacity." (PMID 30622340, 2019). "Collectively, our data support the conclusion that ERα and ZEB1 regulate the expression of SOX9 via regulating miR-190 expression in breast cancer cells." (PMID 30658681, 2019). "Many studies have demonstrated that SOX9 plays active roles during cancer tumorigenesis and progression in various types of cancer, including breast cancer." (PMID 30658681, 2019). "Gene expression profiling has identified SOX9 as one of the signature genes that defines the basal-like subtype of breast cancer." (PMID 30658681, 2019). "Next, breast cancer cells were transfected in combination with miR‐215‐5p and Sox9 to demonstrate that Sox9 was the functional target of miR‐215‐5p." (PMID 31538724, 2019). "By analysing the dataset GSE9195 cohort, we observed an increase in SOX9 transcription level in clinical samples of ER+ breast cancer that were resistant to tamoxifen compared with the sensitive ones." (PMID 31690832, 2019). "Previous in vivo xenograft studies have shown that Sox9 silencing in MDA-MB-231 breast cancer cells reduces tumour formation." (PMID 30622340, 2019). "HDAC5 and SOX9 are related to the poor survival rates in endocrine-therapy-treated ER+ breast cancer." (PMID 31690832, 2019). "Sox9 is important for determining the mammary stem cell state both in normal and breast cancer cell lines." (PMID 30622340, 2019). "We found that miR‐215‐5p reduced the luciferase activity in breast cancer cells transfected with the wt 3'‐UTR of Sox9." (PMID 31538724, 2019). "SLUG and SOX9 play essential roles in induction and maintenance of tumor initiating capacity in breast cancer cells." (PMID 31057614, 2019). "There is also evidence that upregulation of SOX9 affected metastasis and tumorigenesis in breast cancer cells by 5-fold and 40-fold, respectively." (PMID 31057614, 2019). "Further, SOX9 upregulation enhances breast cancer cell proliferation in highly metastatic breast cancers and is an independent marker of poor prognosis and a low 5-year overall survival rate." (PMID 31060551, 2019). "Overall, these results imply that miRNA‐215‐5p suppresses the aggressiveness of breast cancer cells through targeting Sox9." (PMID 31538724, 2019). "In this study, we demonstrated the indispensable role of HDAC5 in mediating the deacetylation and nuclear localisation of SOX9 in tamoxifen resistant breast cancer cells." (PMID 31690832, 2019). "Altogether, these findings verify that miR‐215‐5p represses the growth, migration and invasion of breast cancer cells by modulating Sox9." (PMID 31538724, 2019). "As revealed by all of these data, the inhibitory impact of miR‐215‐5p on the malignant phenotypes of breast cancer cells is rescued by Sox9." (PMID 31538724, 2019). "To corroborate that SOX9 mediates the role of miR-190 in anti-estrogen responses in breast cancer cells, we transfected SOX9 mammalian plasmid into MDA-MB-231 cells in addition to miR-190 overexpression." (PMID 30658681, 2019). "Meanwhile, the colony formation assay proved that down‐regulation of Sox9 substantially lowered the colony formation in breast cancer cells." (PMID 31538724, 2019). "To further investigate the clinical relationship between miR-190 and SOX9, we examined the expression of SOX9 and miR-190 in 30 specimens of primary breast cancer tissues by RT-qPCR." (PMID 30658681, 2019). "Recently, SOX9 was reported to be upregulated in tamoxifen-resistant breast cancer cells and drive breast cancer endocrine resistance." (PMID 30658681, 2019).
breast carcinoma (continued). "Collectively, these results suggest that HDAC5 deacetylates SOX9 to maintain its nuclear localisation, which drives tamoxifen resistance in breast cancer." (PMID 31690832, 2019). "The luciferase reporter gene assay and western blotting assay demonstrated that Sox9 is the potential target of miR‐215‐5p in breast cancer." (PMID 31538724, 2019). "siSox9 was applied for reducing the expression of Sox9, and we explored the down‐regulation of Sox9 on the development of breast cancer cells." (PMID 31538724, 2019). "In our previous study, we observed that miR-190-5p increased the anti-estrogen sensitivity of breast cancer cells and identified SOX9 as a direct target of miR-190-5p." (PMID 31624470, 2019). "Some breast cancers express high levels of Sox9, especially tumours resistant to tamoxifen and ER-negative tumours." (PMID 30622340, 2019). "Together, these findings highlight an inverse correlation between Sox9 and ER expression in breast cancer cells and indicate that Sox9 expression is found in both luminal progenitor cells and more aggressive breast tumours." (PMID 30622340, 2019). "Altogether, these data indicate that cytoplasmic location of SOX9 was directly related with increased proliferation in breast cancer cell lines." (PMID 31057614, 2019). "Re‐expression of Sox9 significantly attenuated the inhibition impact of miR‐215‐5p on the proliferation and colony formation of breast cancer cells." (PMID 31538724, 2019). "For clinical relevance, breast cancer patients with tamoxifen treatment expressing elevated SOX9 and HDAC5 have a worse overall survival." (PMID 31690832, 2019). "Consistently, depletion of SOX9 suppresses the tumor-initiating and metastatic abilities of breast cancer cells." (PMID 30658681, 2019). "Our observations support a model in which Sox9 is required for the maintenance of luminal progenitors in the human breast and for Wnt signalling in tamoxifen-resistant breast cancer cells." (PMID 30622340, 2019). "In summary, in the present study we identified HDAC5, whose transcription promoted by C-MYC, is essential for SOX9 deacetylation and nuclear localisation in tamoxifen-resistant breast cancer." (PMID 31690832, 2019). "Phosphorylation of two corresponding sites in SOX9 (T236 and T239) was detected in breast cancer cells." (PMID 29295999, 2018). "Collectively, these results suggest that Sox9 contributes to the miR-133b-endowed suppression of tumorigenic and metastatic ability of breast cancer cells, whereas WAVE2 only has effect on the cell motility suppression caused by miR-133b." (PMID 29970901, 2018). "Consistently, knockdown of Sox9 suppresses the tumor-initiating ability and metastasis of breast cancer." (PMID 29970901, 2018). "A similar effect was observed in a breast cancer study where overexpression of Sox9 led to micrometastasis in the lung but macrometastases were only observed when cells had increased levels of Slug." (PMID 29484136, 2018). "Previous studies have demonstrated that SNAI2 increases stemness in breast cancer cells when co-expressed with SOX9 or through regulation of stem cell markers, including c-Myc, SOX2 and Oct4, possibly contributing to drug resistance." (PMID 29921289, 2018). "Decreased miR-133b participates in the development and progression of human breast cancer by targeting Sox9 that regulates cancer initiation and metastasis." (PMID 29970901, 2018). "Functional SOX9 knock-down studies using siRNA and cancer stem cell models were generated in a panel of liver and breast cancer cell lines." (PMID 29121666, 2017). "In non-physiological conditions, previous studies revealed the regulatory role of Sox9 on the transcription of Wnt genes in breast cancer cells." (PMID 29158570, 2017). "As SOX9 has been previously discussed as a factor involved in stem cell biology, we generated tumour spheres in a panel of liver and breast cancer cell lines (n = 5) under low attachment condition." (PMID 29121666, 2017).
breast carcinoma (continued). "Altogether these data strengthened our in vitro results concerning the correlation between HDAC9 and SOX9, their higher expression in basal type breast cancers and the deleterious effect of HDAC9 overexpression on breast cancer cell proliferation." (PMID 26930713, 2016). "A recent study reported that SOX9 plays a critical role in supporting mammary epithelial stem cells and enhances breast cancer cell proliferation and metastasis." (PMID 26930713, 2016). "For example, our gene set enrichment analysis found similarity between SOX9Hi SQCCs and certain breast cancers (especially triple negative) and neural crest-derived tumors, whose genesis and malignant properties are affected by SOX9." (PMID 27880766, 2016). "Previous work has shown that SOX9, in cooperation with Slug, supports mammary epithelial stem cells and enhances breast cancer cell metastasis." (PMID 26930713, 2016). "SOX10 suppression contributes to BRAF- and/or MEK-inhibitor resistance in BRAF mutated melanoma, by activating TGFβ signalling to upregulate EGFR and PDGFRB, whilst increasing SOX9 transcript abundance has been observed in breast cancer EMT." (PMID 27852308, 2016). "The transcription factor SOX9 have been identified as a downstream target of different signalling pathways contributing to breast cancer aggressiveness." (PMID 26264004, 2015). "Among these transcription factors, Slug cooperates the transcription factor Sox9 in breast cancer cells and normal mammary stem/progenitor cells." (PMID 26712794, 2015). "Inhibition of either Slug or Sox9 blocks the activities of normal mammary stem/progenitor cells and that of breast cancer cells, suggesting that breast cancer cells and normal stem/progenitor cells are controlled by similar key regulators." (PMID 26712794, 2015). "Being overexpressed and regulated by NF-κB in different types of cancers, SOX9 expression is highly correlated to invasiveness and poor clinical outcome of breast cancer." (PMID 26264004, 2015). "A potential role of Sox9 in regulating mammary stem/progenitor cell functions has emerged from recent studies using ectopic expression and analyses of breast cancer cell lines." (PMID 25527186, 2014). "Down-regulation of Wnt-1-induced signaling protein-2 (WISP2) in relatively well-differentiated MCF7 breast cancer cell line promoted a cancer stem-like cell phenotype with upregulation of SOX9." (PMID 25527186, 2014). "High Sox9 expression in basal-like breast cancer correlates with poor prognosis and activation of Wnt/β-catenin pathway, and SOX9 silencing reduced cell proliferation and invasion." (PMID 25527186, 2014). "We analyzed immunohistochemical expression of Slug, Sox9 and Sox10 in tissue microarrays of 96 breast cancers prior to and after neoadjuvant chemotherapy." (PMID 24404438, 2013). "The aim of this study was to discover the prognostic role of Slug, Sox9 and Sox10 in neoadjuvantly treated breast cancer and the correlation to pathological response and overall survival." (PMID 24404438, 2013). "In our study we analyzed the prognostic role and stability of transcription factors as Sox9, Sox10 and Slug in a cohort of preoperative chemotherapeutically treated breast cancers." (PMID 24404438, 2013). "Co-expression of Slug and Sox9 in breast cancer was found to correlate with rapid tumor growth and metastasis spreading in a study earlier." (PMID 24404438, 2013). "In this study we tested the stability of Slug, Sox9 and Sox10 expression during chemotherapy and addressed their prognostic role of in neoadjuvant treated primary breast-cancer and their correlation to pathological-response and overall survival." (PMID 24404438, 2013). "Subsequently, it emerged that SOX9 has been found to be upregulated in several tumor types, such as lung adenocarcinoma, breast carcinoma, colorectal cancer, and prostate cancer." (PMID 22385677, 2012).
breast carcinoma (continued). "A member of the high mobility group (HMG) box gene family transcription factor, SOX9, is also stimulated by RA, and involved in the RA-mediated growth suppression in breast cancer cells." (PMID 19088887, 2008). "Similarly, research has shown that miR-215-5p targets the oncogenic transcription factor SOX9, effectively inhibiting breast cancer cell invasion, metastasis, and disease progression." (PMID 41230330, 2025). "SOX9 plays a crucial role in breast cancer progression and the preservation of stem cells." (PMID 38725852, 2024). "Several reports have suggested a role for HuR and SOX9 in breast cancer progression, but it was unknown if there was any interconnection between both proteins." (PMID 38254873, 2024). "In addition, the effects of the correlation between SOX2 and SOX9 expression in malignant tumors, such as lung cancer and breast cancer, have attracted attention." (PMID 39684417, 2024). "Altogether, our results suggest that HuR’s role in breast cancer progression could be, at least partly, mediated by the stabilization of SOX9 mRNA." (PMID 38254873, 2024). "Further experiments are needed to determine whether HuR counteracts RBPs or miRNA binding to prevent SOX9 mRNA decay, which will increase our knowledge in the role of HuR in the progression of breast cancer." (PMID 38254873, 2024). "Indeed, one of our POU2F3-positive breast cancers (the only case for which SOX9-IHC was available) clearly expressed SOX9." (PMID 37179317, 2023). "We describe three novel miRNAs targeting SOX9 in human breast cancer cell lines." (PMID 35779228, 2023). "Down-regulation of miR-134-3p and miR-224-3p expression might represent an initial event in breast cancer development, leading to elevated SOX9 levels that will drive breast cancer progression." (PMID 35779228, 2023). "Among them miR-134-2p and miR-224-3p might act as tumor suppressors, whose down-regulation induces elevated SOX9 levels thereby promoting breast cancer progression." (PMID 35779228, 2023). "The transcription factor SOX9 represents an important mediator of breast cancer progression." (PMID 35779228, 2023). "In accordance with the effects observed in MDA-MB-231 cells, we confirmed decreased luminescence signal intensity in MCF-7 and in HEK293 cells to be caused by miR-134-3p and miR-224-3p, suggesting direct SOX9 targeting by these miRNAs across various breast cancer cell lines and HEK293 cells." (PMID 35779228, 2023). "In addition, accumulating studies have indicated a critical role for SOX9 in breast cancer development, maintenance, and progression, particularly in TNBCs." (PMID 37179317, 2023). "Also, SOX9 is overexpressed in many cancers, such as breast cancer, bladder cancer, and prostate cancer." (PMID 35395444, 2022). "Also, a study has proven that miRNA-511-5p prevents malignant behaviors of breast cancer with a direct effect on SOX9 and PI3/AKT regulatory pathway." (PMID 35322101, 2022). "We demonstrated that extracellular ATP could upregulate the expression of SOX9 in breast cancer cells, inducing the expression of SOX9 target genes to reduce drug sensitivity." (PMID 35236823, 2022). "By targeting Sox9, miRNA-215-5p inhibits aggressiveness in breast cancer cells." (PMID 36467881, 2022). "miRNA-613 can specifically bind to the 3'UTR of SOX9, and miRNA-613 may inhibits the proliferation, invasion and metastasis of breast cancer cells and epithelial-mesenchymal transition by regulating SOX9 and Wnt/β-catenin signaling pathway." (PMID 35706002, 2022). "Mechanistic studies reveal that SOX9 regulates Androgen Receptor (AR) expression, drives the WNT signaling pathway activation in prostate cancer, and is associated with endocrine resistance in breast cancer." (PMID 36230806, 2022). "Interestingly, Sox2 and Sox9 have been shown to be critical for the persistence of quiescent stem-like breast cancer cells." (PMID 33985544, 2021).